TNC (tenascin C)
Diseases named in the same sentence as TNC in open-access papers (continued):
Sharing a sentence is not in itself a finding about the gene and the disease.
glioma (continued). "Some studies have shown that larger tenascin-C isoforms are expressed only in tumorous but not in healthy tissues and their expression correlate with cancer progression and poor prognosis in glioma, bladder, ovarian breast, pancreatic, esophageal and lung cancer." (PMID 35008401, 2022). "Although the ECM is clearly a physical barrier that glioma cells must pass through to establish non-delineated paths for invasion, it also provides the appropriate ligands (e.g., integrins, tenascin C) that glioma cells can transiently utilize as anchors to pull themselves forward." (PMID 28821904, 2018). "Since the tenascin c is not strictly a glioma membrane protein, this may be a limiting factor for the direct glioma treatment, and is probably not the optimal way to treat glioma cells." (PMID 21437175, 2010).
glioblastoma (49 papers, 2010 to 2025). The most malignant astrocytic tumor (WHO grade IV). "Cathepsin B and Tenascin-C are highly expressed in malignant anaplastic astrocytomas and glioblastomas when compared to normal brain tissues and are associated with tumor neovessels." (PMID 36980765, 2023). "For the design of additional siRNA-expressing parts, tenascin-C (TNC), a critical oncogene associated with many cancer types, including glioblastoma, was selected as the second siRNA target." (PMID 33782530, 2021). "The aptamer GB1-10 has been shown to recognize a glioblastoma-associated tenascin-C isoform, which is a useful marker for disease activity." (PMID 26041011, 2015). "Both the presence of hypoxic areas and high stiffness have a strong association with poor prognosis in glioblastomas, suggesting that hypoxia-driven production of tenascin C, and its binding to hyaluronan underlie the mechanism of stiffness increase, which fuels glioblastoma progression." (PMID 33330449, 2020). "They observed that the knockdown of tenascin-C in glioblastoma neurosphere cells decreased tumor migration and invasion while increasing tumor proliferation." (PMID 40940872, 2025). "In this instance, elevated TNC+ EV levels remained statistically significant in glioblastoma patientswhen compared to HD, particularly in the case of TNC+/CD9+ EVs (FC = 12.05, p < 0.01)." (PMID 40056466, 2025). "Nonetheless, the significant differences observed in EVs fromboth plasma (by UC and SEC) and CSF samples support the potentialof TNC+/CD9+ EV quantifications as clinicalbiomarkers for glioblastoma, across different methods and liquid biopsysources." (PMID 40056466, 2025). "Mouse xenograft models have shown that mutant IDH1 blocks glioblastoma aggression by reducing the HIF1α-dependent tenascin C expression to decrease extracellular matrix stiffness and mechanosignaling." (PMID 40940872, 2025). "To determine the suitability ofTNC protein to enrich tumor-derived EVs (tEVs) from the circulation,we performed MACS sorting of TNC+ EVs from plasma samplesof glioblastoma patients." (PMID 40056466, 2025). "Although newly diagnosed glioblastoma had the highest plasmafold changes for TNC+/CD63+ EVs than HD, weakor insignificant differences were found for this subpopulation inrecurrent patients compared to HD and post-OP subjects." (PMID 40056466, 2025). "By exploring TNC, whoseexpression has been associated with glioblastomafor a long time, we found that all TNC+ EV subpopulations were elevated in glioblastoma patients,both in newly diagnosed and recurrences." (PMID 40056466, 2025). "A trendof 3.9-fold lower levels for TNC+/CD9+ EVs inRTK-I glioblastoma patients was also observed when compared with themesenchymal (MES) subtype (p < 0.08)." (PMID 40056466, 2025). "We further investigated TNCRNA and protein levels in glioblastoma cells, and identified TNC+ EVs as tEVs." (PMID 40056466, 2025). "Spatial transcriptomicanalysis indicated a TNC overexpression in malignant cell populationsof glioblastoma resections, particularly in cells with mesenchymal-likesignatures and chromosomal aberrations." (PMID 40056466, 2025). "Significant results were also observed for TNC+/CD81+ in newly diagnosed and relapsed patients (FC =5.9 and 6.4, respectively), as well as for TNC+/CD63+ (FC = 10.96 in newly diagnosed glioblastoma; p < 0.001)." (PMID 40056466, 2025). "In vitro, TNC knockdown glioblastoma cell lines were characterized by increased adhesion to the ECM components mediated through the upregulation of the FAK-pathway." (PMID 36980765, 2023). "The nanotags were designed to target the biomarker tenascin-C overexpressed in U87-MG glioblastoma cells." (PMID 37366648, 2023). "Glioblastoma CSCs produce an extracellular matrix protein tenascin-C (TNC), which is packaged into exosomes and transported to the T-cells in both the TME and cardiovascular system." (PMID 36613838, 2022).
glioblastoma (continued). "The proximal TNC promoter contains a crucial RBPJκ binding element and in glioblastoma, TN-C was shown to be trans-activated by Notch2 signaling in an RBPJκ-dependent manner." (PMID 35785162, 2022). "Regulation of NR4A1 and TNC expression in glioblastomas remains unreported; however, TNC is an ECM receptor protein that involves ECM receptor interactions." (PMID 35327982, 2022). "For example, cultured glioblastoma cells can generate basement membrane components, such as Laminin, Vitronectin, Fibronectin, Tenascin C, Collagen I, Collagen IV, or Collagen VI." (PMID 35053605, 2022). "The therapeutic value of our strategy is demonstrated by programmed silencing of critical targets associated with various diseases, including EGFR/KRAS in lung cancer, EGFR/TNC in glioblastoma and PTP1B in obesity." (PMID 33782530, 2021). "A tenascin-c-enriched extracellular matrix in IDH1mt glioblastoma enhances its stiffness, thus reducing glioblastoma aggression." (PMID 33810170, 2021). "TNC is overexpressed in malignant gliomas such as high grade astrocytomas and glioblastomas and promotes the invasion of malignant gliomas." (PMID 32906679, 2020). "Conversely, reducing tenascin C expression in aggressive glioblastoma cells significantly decreases the stiffness of the brain tumor ECM leading to significantly lower tumor aggression." (PMID 33330449, 2020). "Tenascin-C is overexpressed in more than 90% of all glioblastoma cases, and this protein is involved in adhesion, migration, and proliferation with increased proliferation with higher grades of tumor malignancy." (PMID 31354487, 2019). "We have successfully demonstrated a new dsRNA delivery system that harnesses well- characterized magnetic nanoparticles coated with PEI to effectively silence expression of tenascin-C in glioblastoma multiforme cell line." (PMID 30889203, 2019). "Expression level of tenascin-C is closely correlated to poor prognosis in glioblastoma patients, while the substantial role of tenascin-C responsible for aggressive progression in glioblastoma cells has not been clarified." (PMID 31261783, 2019). "Here we report new approach towards RNA interference therapy of glioblastoma multiforme based on the magnetic nanoparticles delivery of the double-stranded RNA (dsRNA) with homological sequences to mRNA of tenascin-C (TN-C), named ATN-RNA." (PMID 30889203, 2019). "The effectiveness of radioactively-labeled antibodies to TNC is being examined in patients with BC, glioblastoma, and head and neck tumors (clinicaltrials.gov)." (PMID 30250408, 2018). "The aptamer TTA1 was developed via a crossover-SELEX protocol with U251 glioblastoma cells and purified human tenascin-C." (PMID 29189740, 2017). "Using this method, an RNA aptamer against Tenascin C (TN-C), a glycoprotein that, in humans, is encoded by the TNC gene and is over-expressed on U251 glioblastoma cells, was identified." (PMID 28146093, 2017). "Radiolabeling GBI-10 with positron emission tomography (PET) isotopes, 18F and 64Cu, developed aptamers capable of imaging tenascin-C within U87MG glioblastoma and MDA-MB-435 breast cancer xenografts in mice." (PMID 29189740, 2017). "EDN3-dependent signalling was shown to counteract the inhibitory effect of TNC on glioblastoma cell adhesion to FN40." (PMID 27905407, 2016). "Several (pre-)clinical studies using tenascin C-targeting agents were performed, in particular in advanced brain tumors such as glioblastoma multiforme and malignant astrocytomas." (PMID 26539408, 2015). "Another example of biomarker discovery using cell-SELEX is the discovery of tenascin-C aptamers using glioblastoma cell line, U251." (PMID 23401749, 2013). "The authors attribute the selection of tenascin-C aptamers using U251 cell lines to the abundance and accessibility of tenascin-C within glioblastoma." (PMID 23401749, 2013).
glioblastoma (continued). "We assessed the expression of the A1 domain of tenascin-C and of the extradomain B of fibronectin (as positive control) in sections of human glioblastoma surgical specimens and of U87MG xenografts in nude mice." (PMID 20736949, 2010). "Importantly,TNC+/CD9+ EVs significantly decreased in newlydiagnosed glioblastoma patients after tumor removal and reincreasedin the same individuals when the tumor recurred." (PMID 40056466, 2025). "TNC+ EV counts from glioblastoma-tissue resections (median = 2.59× 108 per milligram of tissue) were 240-fold higherthan in matched plasma, adding proof that tumor cells are the main sourceof elevated release of TNC+ EVs." (PMID 40056466, 2025). "As we hypothesized that the majority of TNC+ EVs observedin the peripheral blood of glioblastoma patients are released fromTNChigh tumor cells, we sought to also quantify TNC inEVs derived from tumor tissues." (PMID 40056466, 2025). "In conclusion,circulating TNC+ EVs may have potential as clinical biomarkersin glioblastoma, and their purification could improve the identificationof tumor-specific mutations in liquid biopsies." (PMID 40056466, 2025). "In the case of glioblastoma, TNC’s interaction with macrophages, particularly in the absence of CD47, enhances the production of pro-inflammatory factors and recruits TAMs, thus highlighting TNC’s role in manipulating the recruitment and function of immune cells." (PMID 38332915, 2023). "Tenascin-C induced increased expression of the active form of MMP-2 in glioblastoma cells, which was supposed to contribute to continuous PDGF production suggesting a positive feedback loop of tenascin-C/TNIIIA2/PDGF leading to hyper-proliferation of glioblastoma cells." (PMID 35008401, 2022). "Likewise, TNC siRNA levels were increased, and protein levels were reduced in glioblastomas of mice treated with the CMV-RVG-siRE+T circuit." (PMID 33782530, 2021). "The extracellular matrix protein tenascin-C is another target of interest for glioblastoma RIT." (PMID 31354487, 2019). "Furthermore, radiolabelled preparations of monoclonal antibodies specific to the A1 or the D domain of tenascin-C have been investigated for the radioimmunotherapy of patients with glioblastoma." (PMID 20736949, 2010). "Moreover, tenascin-C was detected in exosomes isolated from the blood of glioblastoma patients." (PMID 35008401, 2022). "Collectively, the tenascin-C/TNIIIA2 could be a potential therapeutic target for glioblastoma." (PMID 31261783, 2019). "We compared structures of anti-tenascin C (anti-Tn-C) aptamers, which inhibit brain tumor glioblastoma multiforme (GBM, WHO IV) and selected miRNA." (PMID 25423301, 2014). "Among them, TNC+ and ITGB1+ EVs showed significantly higher levels innewly diagnosed and recurrent glioblastoma patients compared to HDand post-OP subjects." (PMID 40056466, 2025). "Once activated, NF-κB stabilizes C/EBPβ in the “regulatory core” and enhances the vasculogenic mimicry of glioblastoma cells by activating the Ephrin-B2/EPHB4 and Notch pathways through the induction of tenascin C (TNC)." (PMID 39857717, 2025). "Tenascin C (TNC) is an attractive ECM molecule for targeted delivery of therapeutics, being overexpressed in several tumor types (glioblastoma, epithelial carcinoma, lymphomas of B and T cell origin, etc.)and associated with tumor progression and metastasis." (PMID 40944718, 2025). "In glioblastoma cells, TNIIIA2 was also able to stimulate PDGF production that resulted in upregulation of the tenascin-C expression in these cells." (PMID 35008401, 2022). "Another aptamer capable of specifically binding to tenascin-C is GBI-10, a DNA aptamer generated against U251 glioblastoma cells." (PMID 29189740, 2017). "When ATN-RNA, a double-stranded RNA complementary to human tenascin C, was applied locally to patients with advance brain tumors, the drug showed a survival benefit of 18 weeks in grade III astrocytoma and 10 weeks in glioblastoma multiforme." (PMID 26539408, 2015).
glioblastoma (continued). "For the comparison we have chosen anti-tenascin C (anti-Tn-C) aptamers, which inhibit brain tumor glioblastoma multiforme (GBM, WHO IV) through the interaction with Tn-C and selected miRNA hairpins." (PMID 25423301, 2014). "Moreover, in glioblastoma cells and rat brain-derived fibroblasts, tenascin-C upregulated matrix metalloproteinase-2, which has the potential to release TNIIIA2 from tenascin-C." (PMID 31261783, 2019). "In glioblastomas, the growing list of candidate TAAs include the epidermal growth factor receptor (EGFR), tenascin-C (TNC), fatty acid binding protein 5 (FABP5), melanoma-associated antigen 3 (MAGEA3), glioma-expressed antigen 2 (GLEA2), and PHD finger protein 3 (PHF3)." (PMID 25944688, 2015). "Recent studies have shown significant changes in tumor and stromal cell activity during glioblastoma (GBM) progression, resulting in increased deposition of ECM components such as collagen, fibronectin, and tenascin-C." (PMID 40721833, 2025). "In ROC analysis, TNC+/CD9+ EVs exhibitthe greatest sensitivity and specificity values for glioblastoma detection.Finally, the concentration of TNC+/CD9+ EVswas also significantly elevated in CSF samples of glioblastoma patients,although with a lower fold change than in plasma samples." (PMID 40056466, 2025). "Given that glioblastoma cells overexpressTNC and naturally releasehigh amounts of EVs,6,22,23 and that an excess of brain-derived EVs in the blood circulationlikely results from BBB disruption, itappears evident that the majority of TNC+ EVs in the bloodplasma indicate a brain malignancy." (PMID 40056466, 2025).
asthma (33 papers, 2005 to 2025). "Rs2104772 is a SNP within the tenascin-C gene that is associated with a higher incidence for pathological remodeling of airways in asthma and Achilles tendon rupture, which are both associated with aberrant vascular remodeling." (PMID 28384286, 2017). "The implication of the tenascin C in the atopic mechanisms supports its association with atopy and atopic asthma phenotypes in our study, but this gene was also associated with asthma in other studies." (PMID 23148572, 2012). "A coding single nucleotide polymorphism (SNP) in the tenascin-C gene has been linked to asthma in adulthood in the Japanese population." (PMID 21205293, 2011). "Furthermore, we show that RPS4Y1 mediates the expression of integrin subunits α4 and β8, which are associated with tenascin-C, increasing cell adhesion and migration, which are known to contribute to worse asthma outcomes." (PMID 40649992, 2025). "Furthermore, increased expression of TNC has been associated with idiopathic pulmonary fibrosis; however, the understanding of its role(s) in other lung diseases, such as asthma, chronic obstructive pulmonary disease (COPD) and lung cancer, is less advanced." (PMID 36829478, 2023). "As such, we investigated how asthma-associated ECM proteins fibronectin (FN1), tenascin-C (TNC) and collagen 4α1 (COL4A1) are altered at a transcriptional and protein level in the absence of RPS4Y1." (PMID 40649992, 2025). "We identify a complex regulatory function of RPS4Y1 for three pertinent proteins in the context of asthma: fibronectin, tenascin-C (TNC) and collagen 4α1." (PMID 40649992, 2025). "The release of tenascin-C and proinflammatory exosomes in the airway are relevant to the biology of virally induced asthma exacerbation." (PMID 40659888, 2025). "TNC expression was also increased in basal epithelial cells and fibroblasts in patients with asthma and AT2 and endothelial cells in patients with COPD." (PMID 36829478, 2023). "Together, these data suggest that TNC can be expressed by a variety of cell types and that expression of TNC is increased in structural (fibroblast, airway smooth muscle, and endothelium) and immune (T cells and NK cells) cells in patients with asthma." (PMID 36829478, 2023). "We further confirmed this in an independent model of asthma by demonstrating the expression of TNC in lung tissue of allergic mice that had significantly increased recruitment of eosinophils." (PMID 32157178, 2020). "Increased TNC expression was reported in lungs of patients with asthma and chronic lung inflammation." (PMID 32198404, 2020). "Airway epithelial cells from patients with asthma release more tenascin-C (TN-C)-carrying EVs upon rhinovirus infection than healthy ones." (PMID 32850874, 2020). "Tenascin-C (TN-C) is an immunomodulatory extracellular matrix protein present in high quantities in the airway of people with asthma, and expression is also upregulated in nasal lavage fluid in response to RV infection." (PMID 31497021, 2019). "TNC is a matricellular protein that is highly expressed during wound healing and tissue remodeling processes in chronic inflammation, including asthma." (PMID 30473714, 2018). "In line with previous studies, reporting tenascin-C genotype-dependent remodeling of the airway endothelium in asthma, the A/A genotype showed superior gains in muscle capillarization post-exercise as compared to the T/T genotype." (PMID 28384286, 2017). "As tenascin-C strongly induced MMP-1 expression and activity and is expressed in the airways of patients with asthma, tenascin-C was studied in detail." (PMID 24587395, 2014). "We therefore compared gene expression of tenascin-C and collagen-I in four asthma and three control ASM cell cultures by real-time PCR." (PMID 24587395, 2014). "Compared with control ASM, asthma derived cells had significantly increased collagen-I but similar levels of tenascin-C gene expression." (PMID 24587395, 2014).